IL10 (interleukin 10)
Diseases named in the same sentence as IL10 in open-access papers (continued):
Sharing a sentence is not in itself a finding about the gene and the disease.
Granuloma (continued). "There was reduction in the levels of IL-10 in L-GSH-treated granulomas compared to the untreated granulomas." (PMID 29494546, 2018). "Compared to macrophages, MDSCs activated primarily the NF-κB and MAPK pathways and the latter largely contributed to the release of IL-10 and replication of bacteria within in vitro generated granulomas." (PMID 30405617, 2018). "The higher levels of IL-10 in granulomas with lower bacterial loads as compared to granulomas in naïve animals is consistent with this finding." (PMID 30312351, 2018). "Nevertheless, CFU- LNs with granulomas had significantly higher proportions of CD11b+ cells producing IL-10 when compared with CFU+ LNs with granulomas, while CD4+ T cells producing TNF were significantly higher in CFU+ LNs." (PMID 30383808, 2018). "At day 40 PI we see fewer total cytotoxic T cells in TGF-β1 KO and double KO granulomas than baseline and IL-10 KO granulomas." (PMID 29326718, 2017). "We also find that the role of TGF-β1 in granulomas differs from that of IL-10, highlighting a novel differential regulation of cytotoxic T cells and macrophages." (PMID 29326718, 2017). "We also simulated the same 1,500 granulomas with IL-10, TGF-β1, or both IL-10 and TGF-β1 depleted at 200 days PI." (PMID 29326718, 2017). "With this study, we identify TGF-β1 as an important regulatory factor impacting mycobacterial control in granulomas with effects that are distinct from those of IL-10." (PMID 29326718, 2017). "Simulations predicted that 70% of granulomas in our baseline containment set, and 71% in IL-10 depletion set would have sterilizing immunity by 400 days PI." (PMID 29326718, 2017). "For IFN-γ and IL-10, expression was greater only in the caudal mediastinal lymph node granulomas compared to uninfected caudal mediastinal lymph node." (PMID 27902779, 2016). "TNF-α and IFN-γ are particularly important in promoting the formation and function of the granulomas, whereas IL-10 is one of the main negative regulators of the response in both sarcoidosis and TB." (PMID 28127112, 2016). "Cytokines like T-cell derived IL-17, IL-2 and IL-10 are increased in granuloma’s, whereas IL-6 and IL-10 are decreased." (PMID 27304615, 2016). "Among tracheobronchial lymph nodes only IL-10 differed in levels of expression between granulomas and non-granuloma areas, with expression being greater within granulomas than in non-granuloma areas." (PMID 27902779, 2016). "In our study, granulomas that had a higher proportion of T cells producing IL-10 in combination with T cells producing pro-inflammatory cytokines IL-2, TNF or IL-17 were associated with sterilization." (PMID 25611466, 2015). "Surprisingly, there was also a direct correlation of T-1 and T-17 cells with T cells producing IL-10 in individual granulomas." (PMID 25611466, 2015). "The frequencies of IL-10 cytokine producing T cells were significantly lower in granulomas from animals with active disease (1.5%) compared to those infected for ∼11 weeks (9.3%) or with latent infection (5.5%)." (PMID 25611466, 2015). "IL-10 is not usually considered to be produced by T cells making other pro-inflammatory cytokines, although in a minor subset of granulomas examined, there was a small population of T cells (1.2%) that made both IL-10 and IL-17." (PMID 25611466, 2015). "Since Th2 cytokines, IL-4 and IL-10, are known to downmodulate granuloma formations, we also measured their levels in granulomas from the two groups of mice." (PMID 25530957, 2014). "This suggests a potential link in vivo between IL‐10 production by monocytes and clinical manifestation of disease, and indirectly with T‐cell activity and granuloma burden." (PMID 24723379, 2014). "A clinical study evaluated the relation between the extent of granuloma infiltration using an x-ray score and the amount of serum TNFα, IL-6, IL-10, IL-12, angiotensin converting enzyme (ACE), and chitotriosidase (CTO)." (PMID 25180094, 2014).
Granuloma (continued). "The granuloma infiltrated muscle bundles and partly destroyed them, with recruited cells exhibiting elevated levels of Th1 cytokines and chemokines, as well as IL-10; yet bacterial growth remained restricted as compared to B6." (PMID 25210773, 2014). "We also demonstrated that the Th1 cytokines, IFN-γ and IL-2, were detected in early granulomas, while Th2 cytokines, IL-4 and IL-10, were detected in more mature granulomas." (PMID 25530957, 2014). "IL-10−/− granulomas contain large clusters of activated Mφs in the periphery of the structure indicating that they fail to maintain proper levels of immune cell activation." (PMID 23869227, 2013). "In one study, mice treated with anti-IL-10 antibodies in vivo displayed increased hepatic and pulmonary granuloma size, increased eosinophilia, and elevated IFN-γ and IL-5 levels during acute infection." (PMID 23429492, 2013). "Taken together, these results suggest that the parameters in the signaling group are establishing the most beneficial response to the concentrations of TNF-α and IL-10, which is critical to the control of the immune response occurring in a granuloma." (PMID 23869227, 2013). "We show that IL-10 is necessary to control activation levels and to prevent tissue damage in a granuloma." (PMID 23869227, 2013). "The balance of TNF-α and IL-10 concentrations in a granuloma presents a possible new avenue for treatment strategies." (PMID 23869227, 2013). "Granulomas in Irf5-/- mice are characterized by an increased IL-4 and IL-10 response and concomitant low iNOS expression." (PMID 21253574, 2011). "Immunohistochemistry of Mtb-laden lungs show increased IFN-γ, IL-12, IP-10, and TGF-β in granulomas and areas with pneumonitis with reductions in IL-10 and IL-4 compared to controls." (PMID 19753300, 2009). "Notably, mice that did present with granulomas appeared to have changes to lymphoid follicles and enhanced humoral responses, indicated by increased IL-4, IL-5, and IL-10 in splenocyte supernatants." (PMID 40375983, 2025). "Importantly, the blockade of IL-10 signaling partially restored the number of granulomas in the liver of infected malnourished mice." (PMID 39527629, 2024). "considers the progression of sarcoidosis in terms of a granuloma radius represented as a conglomerate of Mφ, Th1, Treg and Th17 cells, which affect each other through a network of cytokines and chemokines (IL-2, IL-10, IL-12, IL-13, chemokine ligand 20, IFN-γ, TNF-α and TGF-β)." (PMID 38550585, 2024). "Regulatory B-cells producing IL-10 and IL-35 were found in TB granulomas." (PMID 37626620, 2023). "Moreover, using ISH, MGCs of early stage I granulomas were shown to express more IL-17A and IL-10, and less TGF-β than MGCs of late-stage IV granulomas." (PMID 35056009, 2022). "This cascade is orchestrated by IL-10 and transforming growth factor beta (TGF-β) in the course of imbalance of proinflammatory and anti-inflammatory signals, causing macrophages/histiocytes to form granulomas." (PMID 34579181, 2021). "Gideon and collaborators also showed pro- (IFNγ) and anti-inflammatory (IL10) cytokine expression by different neutrophil subsets in granulomas from Mtb-infected cynomolgus macaques, suggesting an immunoregulatory function of neutrophils in TB granulomas." (PMID 34887853, 2021). "As the defective formation of granulomas in infected patients may be associated with a decrease in inflammatory cytokines, we measured the release of TNF and IL-10 by cells incubated with BCG-coated beads for 1 and 3 days." (PMID 32411623, 2020). "Increased early IL-10 production and decreased neutrophilia and inflammation observed after infection with the Δmmpl7 mutant likely skewed the immune response toward protective iBALT containing granulomas." (PMID 32695111, 2020). "Furthermore, IL-10 can contribute to the anti-inflammatory environment, and has been correlated with reduction of granulomas in patients with S. mansoni." (PMID 32853206, 2020).
Granuloma (continued). "Indeed, in the present study, global IL-4Rα−/− mice had impaired hepatic granuloma development alongside elevated serum IL-10 levels compared with wild-type control mice and CD4+ T cell specific IL-4Rα−/− mice." (PMID 31475014, 2019). "However, at day 9, IL-10 was significantly increased in granuloma cells treated by etanercept as compared to untreated cells." (PMID 31475008, 2019). "We provide evidences that the anti-TNF-α mediated-decrease of MGC in granuloma may involve an IL-10-dependent defect of cell fusion in the case of etanercept and may result from macrophage apoptosis induction in the case of adalimumab." (PMID 31475008, 2019). "However, IL-10 was significantly higher in both library A and B granulomas in reinfected macaques compared to granulomas in naïve macaques." (PMID 30312351, 2018). "IL-10 has been shown to mediate this down-regulation via an activation-induced cell death process resulting in apoptosis of CD4+ and CD8+ T cells which is also linked to the onset of egg-laying by the helminth parasite and formation of granulomas." (PMID 30048550, 2018). "IL-10 is another anti-inflammatory cytokine expressed by T cells and macrophages in granulomas." (PMID 29326718, 2017). "Whole-slide imaging of hematoxylin and eosin, acid-fast bacilli (AFB), and chromogenic staining for HIV p24, CD3, CD4, CD8, CD15, CD68, interferon γ (IFN-γ), IFN-α, TNF, and IL-10 were used to visualize phenotypic differences within all granulomas and the entire LN section." (PMID 27462092, 2016). "The ability of ART to restore the CD4+ T-cell count and reduce IL-10 production within granulomas of coinfected persons may indirectly lead to reduced M. tuberculosis growth." (PMID 27462092, 2016). "Although most individual T cells appear to primarily produce a single cytokine, the granuloma itself is “poly-functional” since T cells producing T-1, T-17 or IL-10 cytokines are significantly correlated amongst each other within granulomas, and therefore must co-exist within the same granuloma." (PMID 25611466, 2015). "Moreover, granuloma cells characterized by heightened production of IL-10 were found to suppress type 1 immune activation in mycobacterial granulomas, which has long been believed to be an active Th1 immune environment." (PMID 26178192, 2015). "The percentage of TGF-β and IL-10+ cells were also significantly higher in lepromatous (p<0.003, p<0.002 respectively) with Mean% ± SD being 16.55±3.2, as compared to 10.2±2.9 in tuberculoid leprosy granulomas." (PMID 24454972, 2014). "This suggests that β-glucan could play a role in the granuloma formation in sarcoidosis by blocking a defence system in terms of IL-10 secretion." (PMID 25180094, 2014). "However, at six-weeks postinfection reduced numbers of granulomas was detected in IL-10 KO mice compared to wild-type animals." (PMID 24069337, 2013). "However, at later stage of infection (six-weeks), we detected a significant reduction in granuloma numbers in IL-10 KO compared to wild-type livers." (PMID 24069337, 2013). "The role of TGFβ in granuloma pathology is even more complex than that of IL-10." (PMID 23429492, 2013). "Since granuloma in mycobacterial infection is a type-1 granuloma that is promoted by IFNγ and inhibited by IL-10, the higher IL-10 production by iCD8− DC may be the basis for the significantly reduced granuloma formation in its recipients." (PMID 20174628, 2010). "However, T cell production of IL-10, particularly in combination with IL-17, has been associated with granuloma with no culturable bacteria in nonhuman primates (NHPs)." (PMID 33848273, 2021). "Although Th17 cells are associated with aggravation of the pathology in murine model of S. mansoni infection, the high levels of IL-17A and IL-10 may reflect in the regulation of Th2 response, reducing the granuloma size and inflammation, and more efficient granuloma resolution." (PMID 32853206, 2020).
Granuloma (continued). "Th2 cytokines interleukin (IL)-4 and IL-10 were found to be mainly expressed while Th1 cytokine interferon γ (INF-γ) was only expressed in 1 out of 3 patients, moreover, Mhmoud and her associates determined the association between Th2 cytokine namely IL-10 in the granuloma caused by M. mycetomatis." (PMID 31295246, 2019). "Moreover, parameter sensitivity analysis for a granuloma model, showed IL-10 had the strongest influence on myofibroblast numbers at 300 days post infection and indicated IL-10 to play a major role in preventing differentiation of immune cells needed to develop protective immunity." (PMID 29364195, 2018). "We hypothesize that this influx of neutrophils (a proinflammatory response) in LNs of patients with <50 peripheral CD4+ T cells/μL of blood ultimately led to the increased production of IL-10 (an antiinflammatory response), since their presence was positively correlated within caseous granulomas." (PMID 27462092, 2016). "Based on our observation that IL-10 was greatly elevated in the M2 macrophage model induced by IL-4, it can be speculated that the inhibitory role of M2 macrophages in preventing the formation and development of granulomas may be partially mediated by IL-10." (PMID 26091535, 2015). "It is tempting to speculate that the development of granulomas in sarcoidosis is initiated by an inflammation induced by inhaled β-glucan and that this inflammation at higher exposure levels depresses an important defence mechanism in terms of IL-10." (PMID 25180094, 2014). "In the chronic phase, interleukin-10 (IL-10) and transforming growth factor-beta (TGF-β) downregulate the inflammation but also lead to tissue damage, such as fibrosis and granuloma formation." (PMID 40299229, 2025). "On the other hand, granulomas can also provide a protective niche by restricting CD4+ T cells away from the core and inhibiting Th1 cells through IL-10 mediated suppression." (PMID 39861915, 2025). "Again, similar findings were confirmed by immunohistochemistry, which showed that the expression of IFN-γ, IL-10, TGF-β3, and IL-6 at the periphery of granulomas in KO rats were significantly lower than those in WT rats." (PMID 35584107, 2022). "Regulatory T cells secrete IL-10 and TGF-β that suppress the activation of dendritic cells, mediate Th1 and Th2 responses and inhibit granuloma development and fibrosis during S. mansoni infection to promote host survival." (PMID 35839247, 2022). "The role of GM-CSF, IFN-γ, TNF-α, IL-10 and TGF-β in the generation of multinucleated giant cells, that are characteristically present in granulomas was studied, stimulating human monocytes with Paracoccidioides antigen in an in vitro setting." (PMID 33668671, 2021). "The vaccinated and infected mice showed the increased expression of TNF-α, IFN-γ, and IL-6 following expression of the anti-inflammatory genes IL-10 and TGF-β in the liver, justifying the reduction in the number and size of the observed granulomas." (PMID 34992597, 2021). "In the granuloma model, the levels of NO, Tumor necrosis factor-α (TNF-α), interleukin IL-β, and interleukin IL-10 in serum were evaluated." (PMID 30823424, 2019). "Decreasing the size of granuloma tissue, it is well correlated with decreased pro-inflammatory cytokines levels (e.g., TNF-α, and IL-1β), as well as an increased level of IL-10." (PMID 30823424, 2019). "The effects of TGF-β1 on overall granuloma development and function, as well as the interplay between IL-10 and TGF-β1 in regulating inflammation in granulomas remain uncharacterized." (PMID 29326718, 2017). "Peripheral CD4+ T-cell depletion correlated with granulomas that contained fewer CD4+ and CD8+ T cells, less interferon γ, more neutrophils, more interleukin 10 (IL-10), and increased M. tuberculosis numbers." (PMID 27462092, 2016).
Granuloma (continued). "Instead, the appearance of MCs at incipient granulomas and surrounding mature granulomas suggests their contribution in orchestrating granuloma formation and maintenance potentially by the secretion of IL-17, IL-6, IL-8, MCP-1, IL-10, IFN-γ and IL-1β31,32." (PMID 34021178, 2021). "Bacterial burdens did not correlate with expression of IFN-γ, TNF-α, TGF-β, granuloma stage, or lung lesion score, although there was a modest positive correlation with IL-10 expression." (PMID 34026898, 2021). "The study also observed a lack of IL-10 expression in advanced granulomas that correlates with previous findings of progressively decreasing IL-10 in cattle with severe pathology." (PMID 33746980, 2021). "When compared to lymph nodes with live Mtb (CFU+), lymph nodes that were able to clear Mtb (with granulomas but CFU negative) had a significantly higher proportion of CD11b+ cells producing IL-10." (PMID 32790739, 2020). "We found that TNF release decreased in PBMCs from patients unable to form granulomas with no increase in IL-10, suggesting that the modulation of TNF production was not related to the overproduction of IL-10." (PMID 32411623, 2020). "Cellular infiltration is common to Sudanese and South Asian PKDL, but the absence of granuloma in the latter can be attributed to the IL-10 rich milieu, which can inhibit granuloma formation as demonstrated in tuberculosis." (PMID 30679687, 2019). "Many immune cells secrete IL-10, however the source of this cytokine in TB granulomas has not been clearly established." (PMID 30405617, 2018). "In this study using in vitro granuloma model, we observed that TNF-α blockade not only blocks its bioavailability, with significant modulation of granuloma, but also significantly reduces the levels of IL-12p40, IFN-γ, IL-17 and IL-10." (PMID 29543912, 2018). "Treatment of granulomas from T2DM subjects with RIF+NAC resulted in a significant decrease in the levels of IFN-γ and TNF-α, and a significant increase in the levels of IL-10." (PMID 30258443, 2018). "The IL-10 KO showed no significant increase in percent bacterial killing by cytotoxic T-cell activity compared to baseline granulomas." (PMID 29326718, 2017). "Similar to IL-10, IFN-α was more likely to be present in AFB-positive granulomas." (PMID 27462092, 2016). "Because IL-10 can inhibit IFN-α production, and IFN-α can induce IL-10 production to reduce the ability to restrict M. tuberculosis growth, we hypothesize that the presence of IFN-α and IL-10 within granulomas may lead to an increase in M. tuberculosis growth." (PMID 27462092, 2016). "Preliminary data on a small subset of granulomas suggests that most of IL-10 producing T cells in the granulomas are not Foxp3+Tregs, however, larger studies are needed to address the effect of regulatory T cells on other cytokines in granulomas." (PMID 25611466, 2015). "The correlation between IL-17 and IL-10 producing T cells was significant in both non-sterile and sterile granulomas." (PMID 25611466, 2015). "Interestingly, IL-10-/- mice infected with S. mansoni display higher pathology and less well-defined granulomas while patients with severe schistosomiasis produce lower levels of IL-10 than those without fibrosis." (PMID 36263057, 2022). "Moreover, adalimumab, a human monoclonal anti-TNF-α IgG1 inhibited MGC formation in granuloma, without altering IL-10 secretion and induced macrophage apoptosis." (PMID 31475008, 2019). "Despite these findings, the way in which IL-10 functions in uncontrolled growth of Leishmania-induced granulomas in infected non-human primates remains unclear." (PMID 24945284, 2014). "Overall, our data demonstrate that the absence of IL-10 increased the antimycobacterial efficacy of PZA, resulting in improved M. tuberculosis clearance, and fewer granulomas, within the 45-d time frame studied." (PMID 37279084, 2023). "Granuloma stage did have modest positive and negative correlations with TNF-α and IL-10, respectively." (PMID 34026898, 2021).